CDSN (corneodesmosin)
Description:
Important for the epidermal barrier integrity.
Synonyms: D6S586E; HTSS; HTSS1; HYPT2; PSS; PSS1
Tractability: Antibody: its Gene Ontology location is reachable by antibodies, with high confidence; UniProt places it where antibodies can reach, with medium confidence; UniProt predicts a signal peptide or a membrane-spanning region.
Safety:
Unwanted effects reported when the protein is acted on. In parentheses: how it was acted on, where the effect was seen, and who reports it.
thrombocytopenia (source: ClinPGx)
Gene: Protein-coding gene on chromosome 6 (31,115,087 to 31,120,446, reverse strand). Ensembl gene ENSG00000204539.
Subcellular location: Secreted
Pathways (Reactome):
Developmental Biology: Formation of the cornified envelope
Gene Ontology:
Molecular function: protein homodimerization activity
Biological process: amyloid fibril formation; cell-cell adhesion; corneocyte desquamation; negative regulation of cornification; skin morphogenesis; cell adhesion; epidermis development; keratinocyte differentiation
Cellular component: cornified envelope; desmosome; cell-cell junction; plasma membrane; extracellular region
Genetic constraint (gnomAD): Loss-of-function variants: 11 observed, 23.64 expected, observed/expected ratio (o/e) 0.47, 90% interval 0.29 to 0.77. The upper end of that interval is the gene's LOEUF score, 0.77, which puts it in group 3 of 6, group 1 being the genes least tolerant of losing a copy. Missense variants: 598 observed, 663.2 expected, observed/expected ratio (o/e) 0.9, 90% interval 0.84 to 0.96. Synonymous variants: 266 observed, 264.29 expected, observed/expected ratio (o/e) 1.01, 90% interval 0.91 to 1.11.
Homologues: Orthologues: chimpanzee CDSN (99% identical), macaque CDSN (90% identical), dog CDSN (73% identical), pig CDSN (73% identical), rabbit CDSN (71% identical), rat Cdsn (68% identical), mouse Cdsn (66% identical), guinea pig CDSN (61% identical).
Diseases named in the same sentence as CDSN in open-access papers:
CDSN is named in the same sentence as 48 diseases in open-access papers, as found by Europe PMC text mining. Sharing a sentence is not in itself a finding about the gene and the disease. The quoted sentences say what the papers report.
psoriasis (20 papers, 2007 to 2025). An autoimmune condition characterized by red, well-delineated plaques with silvery scales that are usually on the extensor surfaces and scalp. "Although the preceding data suggested a role for CDSN variation in psoriasis etiology, further investigations indicate that the correlation with CDSN alleles is likely secondary, indicating linkage disequilibrium with HLA-Cw6." (PMID 40690118, 2025). "PSORS1 contains HLA-Cw6, the major psoriasis susceptibility allele, located at 6p21.3, as well as the candidate gene corneodesmosin (CDSN), which codifies for a desmosomal protein involved in keratinocyte cohesion and desquamation." (PMID 38256115, 2024). "For example, a synonymous SNP in the corneodesmosin gene induced allele-specific gene expression and led to increased mRNA stability in a psoriasis study across diverse ethnic groups." (PMID 24967893, 2014). "For example, the synonymous SNPs of corneodesmosin was associated with psoriasis onset, the synonymous SNPs of ApoE gene and low-density lipoprotein receptor-related protein 6 gene can increase the risk in developing Alzheimer's disease." (PMID 24596578, 2014). "On the other hand, corneodesmosin SNPs do confer susceptibility to psoriasis in humans." (PMID 25973436, 2015). "Corneodesmosin is expressed in abundance in the psoriatic skin—probably because it is defective and therefore upregulated—in counterpart to normal skin and its expression in psoriasis differs also from other skin diseases associated with proliferation." (PMID 25973436, 2015). "Consistent with this hypothesis, the exC3 cluster contained two genes (SPINK5 and FLG) previously recognised to confer susceptibility to childhood atopic dermatitis (AD), and one (CDSN) which has been implicated in psoriasis." (PMID 19888454, 2009). "Thus, we may hypothesize that in psoriatic men with AA genotype the presence of two alleles that potentially elevate the expression of corneodesmosin in the skin may result in increased severity of psoriasis." (PMID 29589160, 2018). "Three genes contained within this region are associated with psoriasis, namely, HLA-Cw6, CCHCR1 (coiled-coil α-helical rod protein), and CDSN (corneodesmosin)." (PMID 24062996, 2013). "In this study, a family-based association analysis of the PSORS1 locus was performed by analyzing 10 polymorphic microsatellite markers from the PSORS1 region as well as HLA-B, HLA-C and CDSN loci in 163 Chinese families of psoriasis." (PMID 18369457, 2008). "Of the 12 altered protein, 5 protein-disease causalities were supported by MR, i.e., LTA-celiac disease (PIVW = 1.29 × 10−3), IL18BP-Crohn’s disease (PIVW = 4.04 × 10−2), DDR1-Graves’ disease (PIVW = 3.37 × 10−3), CDSN-psoriasis (PIVW = 4.02 × 10−7), and BTN3A2-SD (PIVW = 3.93×10−5)." (PMID 39009607, 2024). "The complete absence of corneodesmosin leads to the peeling skin disease which differs from psoriasis so the variants of corneodesmosin associated with psoriasis likely remain functional at a certain level." (PMID 25973436, 2015). "Because of the thinning or disappearance of the granular layer at psoriasis lesions, the spinous layer may prematurely express the products (such as fatty acid-binding protein, filaggrin, corneodesmosin, glutaminase, involucrin, and loricrin) normally expressed in the granular layer." (PMID 33967781, 2021). "The locus associated with total WBC count on chromosome 6p21 contains genes associated with follicular lymphoma (CHCG22), progression of HIV-1 infection (CDSN, PSORS1C1 and PSORS1C2) and psoriasis (CCHCR1, PSORS1C1 and PSORS1C2)." (PMID 21738480, 2011). "For instance, the glycoprotein corneodesmosin, believed to play a role in psoriasis development, is present in cutaneous epithelia but not in mucosal epithelia." (PMID 38541672, 2024).
hypotrichosis simplex (7 papers, 2020 to 2025). Hypotrichosis simplex (HS) or hereditary hypotrichosis simplex (HHS) is characterized by reduced pilosity over the scalp and body (with sparse, thin, and short hair) in the absence of other anomalies. "It has been reported that CDSN gene mutation causes scalp peeling and hypotrichosis simplex of the scalp." (PMID 36437997, 2022). "Mutations in CDSN have been described in hereditary skin conditions such as hypotrichosis simplex of the scalp (HSS) and progressive loss of scalp hair (PSD)." (PMID 35096593, 2021). "Our study strengthens the previously established link between mutations in CDSN to peeling skin disease and hypotrichosis simplex of the scalp." (PMID 31663161, 2020). "Monoallelic mutations in CDSN have also been described in an autosomal dominant inherited genodermatosis: hypotrichosis simplex of the scalp." (PMID 31663161, 2020). "The formation of short chains and the gradual accumulation of amyloid aggregates of desmosome proteins composed of normal CDSN genes, which may be toxic during hair growth, and are thus involved in the pathogenic mechanisms of hypotrichosis simplex of the scalp (HSS)." (PMID 39902296, 2024). "Hypotrichosis simplex of the scalp (HSS) is a clinically rare monogenic autosomal dominant disorder associated with variants in the gene CDSN, which encodes the desmosome protein corneodesmosin." (PMID 39902296, 2024). "Previous studies have reported many casual genes associated with heredity hypotrichosis simplex such as LSS, CDSN, and APCDD1, while other studies highlighted that CDH3 variants cause hypotrichosis simplex with juvenile macular dystrophy (HJMD; OMIM #601553) that is manifested later in life." (PMID 35962736, 2022). "Studies had found that mutations in the CDSN gene could cause excessive keratosis of the skin, and lead to peeling skin disease and hypotrichosis simplex of the scalp, therefore, down-regulation of CDSN may accelerate the development of CM by slowing down epidermal development." (PMID 33240619, 2020). "There is currently no definitive and effective treatment for hypotrichosis simplex of the scalp, this paper shows that minoxidil in combination with botanical extracts significantly improves HSS caused by mutations in the CDSN gene." (PMID 39902296, 2024).
melanoma (3 papers, 2020 to 2023). A malignant, usually aggressive tumor composed of atypical, neoplastic melanocytes. "Overall, this systematic meta-analysis of gene profiling was a step forward in the investigation of the mechanisms underlying melanoma's metastasis, and the role of SPRR1B, SPRR2B, TGM1, CDSN, and IVL in keratinocyte differentiation GO term needs to be further studied." (PMID 35003328, 2021). "But the report of SPRR1B, SPRR2B, TGM1, CDSN, and IVL in melanoma was a gap." (PMID 35003328, 2021).
Peeling skin disease (3 papers, 2021 to 2025). "Peeling skin disease (PSD) was the first genodermatosis described to be caused by mutations in the corneodesmosin (CDSN) gene." (PMID 35806491, 2022).
asthma (2 papers, 2020 to 2024). "The differentially expressed genes included those related to inflammation (CCL22, CXCL16, AREG, MMP12) involved in asthma pathophysiology, as well as genes associated with the skin barrier (IVL, CDSN, SPINK5, FLG)." (PMID 39451560, 2024).
peeling skin syndrome 1 (2 papers, 2025). Any peeling skin syndrome in which the cause of the disease is a mutation in the CDSN gene. "Corneodesmosin-nonsyndromic Epidermal Differentiation Disorder [CDSN-nEDD (formerly Peeling skin syndrome type 1, OMIM270300)] is a very rare autosomal recessive form of congenital ichthyosis." (PMID 40943523, 2025). "Congenital ichthyoses, now grouped under the acronym EDD (Epidermal Differentiation Disorders), include nonsyndromic forms (nEDD) that may be caused by loss-of-function mutations in the CDSN gene encoding corneodesmosin (CDSN-nEDD, formerly Peeling skin syndrome type 1)." (PMID 40943523, 2025).
food allergies (1 paper, 2011). "Still, the observation that humans with genetic defects in CDSN also display food allergies suggests that the protein may play a role in processes unrelated to skin function." (PMID 21682861, 2011).
leprosy (1 paper, 2021). Leprosy is a chronic infectious disease affecting primarily the skin and peripheral nervous system. "We identified mutations in four genes (IL18R1, BCL10, CDSN, and PSORS1C2) as candidates for functional mediators of leprosy susceptibility." (PMID 34879060, 2021).
prostate carcinoma (1 paper, 2025). A carcinoma that arises from epithelial cells of the prostate gland. "Proteins unique to the U-EVs of the GS 6–7 group included several keratins, corneodesmosin, the cell–cell adhesion protein desmoplakin, and uroplakin-2, which is a marker for urothelial and prostate carcinoma." (PMID 40725142, 2025).
skin disorder (2 papers, 2016 to 2021). Any deviation from the normal structure or function of the skin or subcutaneous tissue that is manifested by a characteristic set of symptoms and signs. "It is interesting that many of the changes in gene expression found in HaCaT-IKKα skin equivalents are relative to genes involved in the development of different skin disorders (CNFN, CDSN, TGM1, ALOX12B, etc)." (PMID 27732959, 2016).
tumor (2 papers, 2021). "The two hypomethylated hub genes, CTLA4 and CDSN, were significantly upregulated, and two hypermethylated hub genes, ACTN2 and MYH11, were downregulated in the HNSC tumor samples." (PMID 35096593, 2021). "In addition, we also verified four hub genes (CTLA4, CDSN, ACTN2, and MYH11) that their expression levels in tumor tissue might be regulated by the mechanism of DNA methylation." (PMID 35096593, 2021).
infection (1 paper, 2021). The state of being infected such as from the introduction of a foreign agent such as serum, vaccine, antigenic substance or organism. "These loci exhibited negative (ELN, SASH1, and SMAD7) and positive (CDSN, NCSTN, and PEX7) relationships between minor allele frequency and infection severity, with no overarching pattern evident in control loci lacking association with mange severity." (PMID 33664786, 2021).
CDSN also shares sentences with these, for which no sentence is quoted: atopic dermatitis (3 papers); ichthyosis vulgaris (3); Palmoplantar keratoderma (3); autosomal recessive congenital ichthyosis (2); ectodermal dysplasia (2); eczema (2); genodermatosis (2); Hyperkeratosis (2); hypotrichosis (2); ichthyosis (2); metastatic melanoma (2); alopecia (1); Alzheimer disease (1); amyloidosis (1); celiac disease (1); Comèl-Netherton syndrome (1); Crohn disease (1); cutis laxa (1); dermatitis (1); dyskeratosis congenita (1); follicular lymphoma (1); Graves disease (1); hidradenitis suppurativa (1); HIV-1 infection (1); hyperplasia (1); hypohidrosis (1); ichthyosiform erythroderma (1); ichthyosis linearis circumflexa (1); inflammatory skin disease (1); keratolytic winter erythema (1).
A further 6 diseases each share a sentence with CDSN in 1 paper.